IL6 (interleukin 6)
Diseases named in the same sentence as IL6 in open-access papers (continued):
Sharing a sentence is not in itself a finding about the gene and the disease.
breast cancer (continued). "Unpublished data from our group show that OB EVs are enriched in palmitic acid and fatty acid binding protein 4 (FABP4), a molecule known to promote breast cancer progression through the IL-6/STAT3/ALDH1 pathway." (PMID 40485730, 2025). "Previous studies have reported significant differences in serum IL-6 levels between healthy donors and early-stage breast cancer patients." (PMID 41226910, 2025). "While the control group generally exhibited low baseline levels of circulating cytokines, breast cancer patients demonstrated significantly elevated concentrations of multiple cytokines, including IL-1β, IL-6, IL-8, IL-12 (p40), IL-13, G-CSF, TNF-α, and MCP-1." (PMID 40612845, 2025). "Homeodomain-containing gene 10 contributed to breast cancer malignant behaviors by activating Interleukin-6/Janus kinase 2/Signal transducer and activator of transcription 3 pathway." (PMID 40267127, 2025). "Using these two strategies, we assessed the therapeutic activity of anti-PD1 in combination with AMD3100, a small molecule antagonizing CXCR4, and anti-IL6 neutralizing antibodies, on immunotherapy-resistant triple negative 4T1 breast cancer." (PMID 40822347, 2025). "In breast cancer, the TME is inhibited by increased levels of cytokines, including TNF-α and IL-6, which are associated with both immunosuppression and tumorigenesis." (PMID 40008130, 2025). "In breast cancer (BrCa), IL6 expression correlates with worse clinical scenarios, such as metastasis and antitumoral therapy resistance." (PMID 40143084, 2025). "This unique Notch signaling activates IL-6/JAK/STAT pathways in breast cancer cells and is modulated by IKKα/IKKβ within the NF-κB signaling cascade." (PMID 41050674, 2025). "IL-8 typically recruits and activates macrophages upon tissue over-injury, induces epithelial–mesenchymal transition, and, combined with an IL-6 to IL-8 ratio of 3.0, upregulates cyclin D1 to drive breast cancer cell proliferation." (PMID 40427296, 2025). "Exosomes from breast cancer (BC) contain cSERPINE2, which shuttles to TAMs to increase IL‐6 secretion and NF‐κB signaling." (PMID 40356340, 2025). "IL-6, for instance, is upregulated in over half of breast cancer patients, with elevated levels particularly noted in early-stage or high-grade tumors." (PMID 40909271, 2025). "Considering the importance of this observation, the role of PIM1 in the regulation of metastasis has also been linked to the interleukin-6 (IL-6)-induced epithelial mesenchymal transition (EMT) and stemness in breast cancer." (PMID 40378957, 2025). "Interleukin-6 (IL-6), a prominent cytokine in the tumor microenvironment (TME) of breast cancer (TNBC), has been implicated in promoting TNBC metastasis." (PMID 40616161, 2025). "STAT3 can be activated in breast cancer by a number of cytokines and growth factors, including interleukin-6 (IL-6), OSM, IGF, FGF, and EGF." (PMID 40507264, 2025). "In summary, this study shows that solid stress compression can lead to upregulation of IL-6 levels and signalling which in turn contribute towards metastatic behaviour of breast cancer cells." (PMID 40371393, 2025). "In a study comparing serum levels of inflammatory cytokines between patients with ductal carcinoma and healthy controls, it was found that IL-6 and interleukin-8 (IL-8) content were markedly elevated in the breast cancer group." (PMID 40906676, 2025). "In a mouse model of breast cancer lung metastasis, Ganoderma lucidum spore oil boosts NK cell activity in the spleen, increases CD8+ T cell and IL-6 levels in the blood, and inhibits the lung metastasis of circulating breast cancer cells." (PMID 40303301, 2025). "Inhibition of IL-6 signalling pathway through neutralising IL-6 antibody and siRNA found both breast cancer cell lines exhibited decreased migratory and invasive potential with reduced SNAI1 transcription." (PMID 40371393, 2025).
breast cancer (continued). "For example, 16 weeks of RT-HIIT reduced IL-6 and soluble CD8a levels in chemotherapy-treated breast cancer patients, improving systemic and physical fatigue by 32.0% and 31.2%, respectively." (PMID 40699773, 2025). "For example, adipocyte-derived leptin and IL-6 can promote breast cancer cell metastasis by increasing the expression of lysyl hydroxylase (an enzyme in collagen synthesis) in tumor cells." (PMID 40863244, 2025). "CD133high BCSCs display resistance to hormonal therapy and promote metastasis via IL-6/Notch3 signaling in ER+ breast cancer." (PMID 40843360, 2025). "Despite its limitations, this assay confirmed that IL-6 directly affects HER2+ mammary tumour cells in a solitary state, which reproduced the IL-6 response observed in vivo." (PMID 40739350, 2025). "In breast tumors, IL-6 levels are often elevated compared to normal tissue, and breast cancer patients frequently show high IL-6 in serum." (PMID 41007766, 2025). "Interleukin-6 expression contributes to lapatinib resistance through maintenance of the stemness property in HER2-positive breast cancer cells." (PMID 40558287, 2025). "To investigate the relationship between eribulin treatment and IL‐6 production in vitro, we assessed IL‐6 levels in the culture supernatants of breast cancer cells treated with increasing concentrations of eribulin." (PMID 41189442, 2025). "Activation of the IL-6/JAK/STAT3 pathway has been reported in many tumor types including breast, and additionally elevated serum levels of IL-6 in breast cancer patients have been linked to poor prognosis." (PMID 40597443, 2025). "Propagermanium, a CCL2 inhibitor, has shown promising results, downregulating serum IL‐6 levels in a phase I clinical trial, as well as demonstrating clinical safety and holding potential as an antimetastatic agent in breast cancer treatment." (PMID 39749673, 2025). "An early-phase clinical trial has tested tocilizumab combined with chemotherapy in breast cancer patients: the initial results showed that adding IL-6 blockade was feasible and safe, although definitive efficacy data are still pending." (PMID 41007766, 2025). "A recent study found that serum levels of cytokines, such as TNF-α, IL-6, IL-8, and IL-10, differ significantly between patients with breast cancer menopause and controls." (PMID 40584290, 2025). "Exosome‐mediated immune suppression was demonstrated in a study where exosomes from TS/A murine mammary tumors partially induced IL‐6 mRNA, inhibiting the differentiation of myeloid precursors into DCs." (PMID 40079186, 2025). "IL-6 expression tends to increase primarily in lung and breast cancer cell lines, especially those with high baseline IL-6 expression, whereas CXCL8 expression shows a less consistent pattern increasing in some cell lines but not in others." (PMID 41264145, 2025). "Secreted IL-6 cytokines would then function in autocrine and paracrine manners to exacerbate breast cancer progression." (PMID 40371393, 2025). "As we show in glioblastoma, IL-1β initiates a cascade of events similar to that in aggressive luminal-type breast cancer cell where mRNA and protein levels of MyD88 induce and activate NFĸB, which in turn activates IL-6 for activation of Calcineurin." (PMID 40725140, 2025). "Additional results are awaited to clarify the clinical impact of IL-6 inhibition on improving therapeutic outcomes for breast cancer patients." (PMID 40558287, 2025). "Specifically, various growth factors and molecular pathways, such as TGF-β1/Smad, PI3 K/AKT, adipsin, CXCL1/8, CK 18+19, and interleukin-6, potentially contribute to the tumor microenvironment and tumorigenesis in breast cancer cells." (PMID 40399731, 2025). "For instance, IL‐6 and IL‐8 secreted by breast cancer cells induce EMT and promote acquisition of more aggressive phenotypes." (PMID 41427020, 2025).
breast cancer (continued). "Breast cancer cells can migrate and invade in vitro when exposed to SASPs, particularly those that significantly generate IL-6 from the senescent MDA-MB-231 breast cancer cell line and the senescent MCF-10A regular epithelial cell line." (PMID 40584290, 2025). "Cytokines such as IL-6 and TNF-alpha have been consistently associated with lower overall survival and unfavorable response in women with breast cancer." (PMID 40558287, 2025). "Cd also induced epidermal growth factor receptor (EGFR), one of the important factors for IL-1 and IL-6, in breast cancer cells and human lung adenocarcinoma cell lines (A549)." (PMID 40771401, 2025). "In breast cancer, tumor‐derived IL‐6 exerts both autocrine and paracrine effects, promoting cancer cell survival and modulating the tumor immune microenvironment." (PMID 41189442, 2025). "Regular exercise reduces the resting levels of intratumoral IL-6 correlating with a reduced tumor size in breast cancer-bearing mice." (PMID 40281902, 2025). "We previously identified serum IL‐6 as a prognostic biomarker in patients with advanced recurrent breast cancer undergoing eribulin therapy, implicating IL‐6 in the development of drug resistance." (PMID 41189442, 2025). "In contrast, M2-like macrophages dominate the TME and drive immunosuppression through distinct mediators, such as IL-1β in CRC, IL-1β/IL-6/TNF-α in breast cancer." (PMID 40380196, 2025). "For instance, in breast cancer, CAF‐derived IL‐6 has been implicated in enhancing tumor progression and radioresistance." (PMID 41395115, 2025). "IL-1β stimulates the secretion of IL-6 by activating NF-kB signaling pathway, which promotes the progression and invasiveness of breast cancer." (PMID 40863244, 2025). "In breast cancer and pancreatic ductal adenocarcinoma, iCAFs influence the immunosuppressive microenvironment by secreting inflammatory factors such as IL-6." (PMID 41408647, 2025). "CAFs-derived IL-6 enhances breast cancer cell invasion and progression from in situ to invasive cancer, while promoting resistance to apoptosis in luminal cancer cells." (PMID 40230452, 2025). "Nevertheless, the stemness maintenance and survival of CSC has been demonstrated to be based on the activation of STAT3 and, particularly, IL6/JAK/STAT3 is activated in breast cancer stem cells." (PMID 39859345, 2025). "Statement of Retraction: Homeodomain-containing gene 10 contributed to breast cancer malignant behaviors by activating Interleukin-6/Janus kinase 2/Signal transducer and activator of transcription 3 pathway." (PMID 40267127, 2025). "The feedback loop further enhances IL-6 expression via activated STAT3, rendering IL-6 less effective in breast cancer cells with low STAT3 expression." (PMID 40909271, 2025). "Functionally, interleukin-6 (IL-6) acts directly on dormant breast cancer cells by promoting their re-entry into the cell cycle." (PMID 40977686, 2025). "The role of IL-6 in breast cancer biology is highly nuanced and strongly dependent on cellular context." (PMID 41514893, 2025). "Clinical studies on breast cancer patients found elevated IL-6 levels at both the edges of breast tumour masses and in patient’s sera as a consequence of overexpression and secretion by breast cancer cells." (PMID 40371393, 2025). "Critically, BPA-exposed adipocytes show increased expression of inflammatory cytokines, IL-6, IL-1β, and TNFα, which are known to activate key oncogenic pathways in breast cancer cells, such as STAT3 and NF-κB." (PMID 40034592, 2025). "Proinflammatory factors, such as TNF-α, IL-1β, and IL-6, influence the development and progression of mammary tumors." (PMID 40526430, 2025). "Elevated plasma levels of leptin and IL-6 were noted in a postmenopausal obesity tumor-bearing mouse model of breast cancer." (PMID 40303301, 2025).
breast cancer (continued). "Under synergistic stimulation of extracellular IL‐6 and IL‐8, breast cancer cells amplify secretion of IL‐6 and IL‐8 to intensify tumor‐related inflammatory environment by self‐enhancing feedback." (PMID 41427020, 2025). "For instance, resveratrol improves chemosensitivity in breast cancer by reversing macrophage polarization, lowering IL‐6 levels, and inhibiting STAT3 activation." (PMID 41394539, 2025). "Given the prominence of IL-6 in breast cancer migration, invasion and metastasis, we evaluated the Normalised Enrichment Score (NES) of the IL-6 signalling in our data set." (PMID 40371393, 2025). "Prior studies have described divergent functions of IL-6, ranging from growth-inhibitory activity in certain breast cancer cell lines to growth-promoting or drug-resistance-associated effects in MCF-7 cells." (PMID 41514893, 2025). "In conclusion, IL-6 and TNF-alpha emerge as prognostic inflammatory biomarkers in women with breast cancer and are associated with poor survival and poor treatment response." (PMID 40558287, 2025). "The results indicate that the GPR30 receptor is involved in cell proliferation induced by IL-6 and E2 in breast cancer and IL-6-induced metastatic properties, such as migration and invasion in luminal, TMX-resistant, and triple-negative cancer cells." (PMID 39201674, 2024). "In particular, components such as IL6 and leptin have been demonstrated to play a significant role in resistance to treatments like Tamoxifen and Paclitaxel in breast cancer patients." (PMID 39767718, 2024). "A similar study in breast cancer showed that PBMC-derived macrophages treated with cancer cell conditioned media and cisplatin had increased IFNγ, IL6, and TNFα signaling, pathways typically associated with M1-like phenotypes." (PMID 39287565, 2024). "IL-6 cytokines are frequently overexpressed in the tumor microenvironment across various cancers, including breast cancer." (PMID 39738201, 2024). "Our experimental results confirmed that levels of IL‐15 or IL‐6 in the peripheral blood of breast cancer model mice subjected to exercise intervention were significantly elevated." (PMID 38234174, 2024). "IL-6 expression is a critical step of breast cancer metastasis, leading to the activation of the JAK2/STAT3 signaling pathway that promotes proliferation, invasion, metastasis, and angiogenesis and inhibits apoptosis in breast cancers." (PMID 38673967, 2024). "In overall breast cancers, MCT-1 expression was more positively associated with IL-6 (r = 0.43, p < 0.001) than with CXCL7 (r = 0.2, p = 0.02) and PD-L1 (r = 0.26, p = 0.003)." (PMID 38505617, 2024). "The dysregulation of the immune system was further explored by analyzing the signaling response to IL-6 or IFN-γ by PBMCs from breast cancer patients." (PMID 39518029, 2024). "Based on this, we evaluated the effect of E2 and IL-6 on breast cancer cell proliferation by trypan blue exclusion assay and mitomycin C (Mit C) as an antiproliferative control." (PMID 39201674, 2024). "Treatment with the senolytic drugs Dasatinib + Quercetin (DQ) prevented or reduced the increased expression of p16Ink4a, Mmp13, and Il6, supporting a direct link between the changes in gene expression and the cellular senescence induced by breast cancer cells." (PMID 38558984, 2024). "For example, it has been demonstrated that tumor-associated fibroblasts are a powerful stimulus for the induction of breast cancer cell-derived hepcidin, and this induction relies on the fibroblast-dependent secretion of IL-6." (PMID 39682254, 2024). "Propofol reduced the production of interleukin-6 (IL-6) and IL-8 in trastuzumab-resistant breast cancer cells while inhibiting the formation of mammospheres and the EMT." (PMID 38482052, 2024). "In breast cancer models, docetaxel has been shown to awaken dormant cancer cells by injuring stromal cells, leading to the release of IL-6 and granulocyte colony-stimulating factor (G-CSF)." (PMID 39682769, 2024).
breast cancer (continued). "IL-6 synthesis by PBMCs from patients with hepatocellular carcinoma and breast cancer was found to correlate with prognosis." (PMID 39518029, 2024). "For example, IL‐6 derived from breast cancer cells induces PGE2 production by infiltrating MSCs, subsequently promoting breast cell growth." (PMID 39070181, 2024). "Secreted from CAFs, both Il-6 and Il-8 are proangiogenic factors, and Il-6 induces proangiogenic effects via the IL-6/STAT3/NF‐κB positive feedback loop in breast cancer and is regulated by WNT2 in CRC." (PMID 39075612, 2024). "Specifically, fermented milk inhibited breast cancer cell proliferation, reduced tumor size, and modulated cytokines (downregulated IL-6 levels and upregulated TNF-α, IL-4, and IL-10 levels)." (PMID 39605907, 2024). "The IL-6 signaling pathway is frequently activated in breast cancer and can promote tumor cell growth while also suppressing the antitumor immune response." (PMID 39735530, 2024). "These authors further demonstrated that FA2H suppresses cancer stemness in breast cancer cells by inhibiting the STAT3/IL6 axis and NFkB signalling." (PMID 39233332, 2024). "Fibroblasts also produce pro-inflammatory IL-6 promoting the growth and radio resistance of breast cancer cells." (PMID 37975220, 2024). "Breast cancer is characterized by increased IL-6 levels which is suspected to be a result of single nucleotide polymorphisms (SNPs) and is associated with poor prognosis in patients." (PMID 38892394, 2024). "Longitudinal studies have shown that increased fatigue symptoms, particularly in women with early-stage breast cancer, are linked to high levels of neutrophil/monocyte, IL1RA, and IL6 during radiation therapy." (PMID 39564104, 2024). "Using this combined activation signature, we found that tGLI1 and IL-6/IL-6R/GP130 signaling pathways were significantly enriched in HER2-enriched breast cancer (N = 96) and TNBC (N = 166) patients when compared to luminal subtypes (N = 247)." (PMID 39768178, 2024). "IL-6 is also upregulated in a variety of other cancers like pancreatic cancer, non-small-cell lung cancer, breast cancer, ovarian cancers and melanoma." (PMID 39099925, 2024). "Hallmark Il6 Jak Stat3 Signaling (Overlap Genes: INHBE, REG1A): This signaling pathway is involved in inflammation and immune responses and has been linked to breast cancer progression and metastasis." (PMID 39000413, 2024). "As a final example, InterLeukin-6 (IL-6) has been shown to increase the migration of breast cancer cells, and it also enhances the survival of invasive tumor cells by acting as an anti-apoptotic factor." (PMID 38542380, 2024). "Our in vivo and in vitro studies support that, in the context of breast cancer, senescent osteocytes have increased osteoclastogenic potential (increased Rankl, Mmp13, Il6) and are key drivers of cancer-induced bone resorption." (PMID 38558984, 2024). "In sporadic breast cancers, tumour cell secretion of cytokines, such as IL-6, basic fibroblast growth factor, and platelet-derived growth factor (PDGF) α/β, transforms normal fibroblasts (NFs) into CAFs." (PMID 39682099, 2024). "Numerous studies have highlighted the efficacy of BZA through the IL-6/GP130 pathway in breast cancer and many other cancer types." (PMID 39451730, 2024). "This study aims to elucidate the role of GPR30 in IL-6-induced metastatic properties of MCF-7 luminal breast cancer cells." (PMID 39201674, 2024). "It has been found to increase the level of the tumor suppressor miR-149-5p and downregulate IL-6 expression, thus making trastuzumab-resistant breast cancer cells sensitive to epigenetic modifications." (PMID 38482052, 2024). "The authors also demonstrated that pro-inflammatory cytokine IL-6 can induce epithelial-to-mesenchymal transition (EMT) of primary epithelial breast cancer cells." (PMID 39796103, 2024).